APEX1 (apurinic/apyrimidinic endodeoxyribonuclease 1)
Diseases named in the same sentence as APEX1 in open-access papers (continued):
Sharing a sentence is not in itself a finding about the gene and the disease.
tumor (172 papers, 2006 to 2026). "The APEX1 redox selective inhibitor E3330 caused a significant inhibition of tumor cell migration in PDAC." (PMID 35626021, 2022). "Following 48 h of exposure, the tumor cells were analyzed for the expression of apoptosis and proliferation markers, such as Caspase-9 and Ki-67, as well as markers associated with cisplatin resistance, including APEX1, MTDH, ERK1, and STAT3." (PMID 40149331, 2025). "In addition, previous studies have shown that APEX1 expression levels in HNC tumor tissues are significantly higher than those in normal tissues, and that high APEX1 expression is associated with an increased risk of HNC in the Pakistani population." (PMID 36338767, 2022). "APEX1 increased expression was described to be associated with a trend toward a reduced chemotherapy response and to significantly correlate with development of tumor recurrence and metastasis." (PMID 34207685, 2021). "The results confirmed that APEX1 expression was higher in tumor tissues than in paracancerous tissues." (PMID 40495893, 2025). "The results showed that the content of APEX1 in both cytoplasm and nucleus was decreased in the tumor cells treated with Isoliensinine." (PMID 40495893, 2025). "In this study, we found that GBC patients with APEX1 positive expression presented a lager tumor size, and down-regulating APEX1 in CD133+ GBC-SD cells was capable of suppressing tumor growth in vivo." (PMID 37283798, 2023). "Next, we investigated the role of APEX1 and Jagged1 in tumor formation in vivo applying mouse xenograft models." (PMID 37283798, 2023). "In gallbladder SC/ASC, APEX1 positive expression was significantly correlated to lager tumor size (˃3cm), lymph node metastasis, locoregional invasion, advanced TNM stages (III + IV), and only received biopsy (all P < 0.05)." (PMID 37283798, 2023). "As a key rate-limiting enzyme in DNA BER pathway, APEX1 functions an irreplaceable role in tumor chemotherapy resistance." (PMID 37283798, 2023). "We suggest that APEX1 overexpression can inhibit the accumulation of lipid peroxidation, thereby promoting the survival of the tumor cells." (PMID 35311089, 2022). "Previous studies have shown that apurinic-apyrimidinic endonuclease-1 (APEX1) is involved in tumor progression." (PMID 35780128, 2022). "It has been shown that there are significantly higher levels of APEX1 protein in tumor cells compared to normal cells." (PMID 36205565, 2022). "To investigate the role of APEX1 in HCC tumor growth in vivo, we established a tumorigenesis model by subcutaneously injecting the sh-APEX1-transfected HCC cell line Bel-7402 into a nude mouse model." (PMID 36205565, 2022). "There is an interesting phenomenon: the expression of APEX1 in tumor cells is increased compared to the non-tumor regions, that can resist ROS induced apoptosis." (PMID 35311089, 2022). "Next, we analyzed APEX1 expression in HCC specimens from different tumor stages in the TCGA database." (PMID 32167932, 2020). "QRT-PCR analysis of 45 paired HCC patient samples showed that APEX1 mRNA levels were significantly higher in tumor tissues compared to paired adjacent normal liver tissues." (PMID 32167932, 2020). "Our evaluation of APEX1 expression and clinicopathological data revealed a correlation between cytoplasmic APEX1 expression in tumor cells and shorter DFS times in patients with HCC or intrahepatic CC." (PMID 31375000, 2019). "In support of angiogenesis and tumor progression, Apex1 also enhances the DNA binding activity of a number of transcription factors and is considered to be a promising target for the consolidation of chemotherapy based on cisplatin." (PMID 27602772, 2016). "The elevation in APEX1 was paralleled by an increase in HYOU1, a heat shock protein, which has important roles in hypoxia and angiogenesis and is linked to tumor prognosis." (PMID 27799870, 2016).
tumor (continued). "In the same hospital, significantly different expressions between matched tumour and healthy adjacent tissues were observed for 6 genes (APEX1, DDB1, ERCC1, NEIL1, PARP1, RPA2) after snap freezing collection." (PMID 27383461, 2016). "Reduced APEX1 protein expression demonstrated a reduction in tumor volume and FDG uptake, indicating that APEX1 affects glucose metabolism and cellular proliferation." (PMID 20540786, 2010). "For the gene APEX1, gene expression data is available in the gene expression data repository Oncomine that shows increasing expression according to tumour malignancy." (PMID 17531100, 2007). "Blocking APEX1 redox activity synergizes with STAT3 inhibitor to enhance tumor cell apoptosis." (PMID 40243693, 2025). "In addition, we demonstrated that Isoliensinine regulates the cell cycle and apoptosis by inhibiting APEX1, thereby promoting the generation of ROS to exert anti-tumor effects." (PMID 40495893, 2025). "The APEX1-AP-1 interplay has significant outcomes in tumor cell behaviors and the immune system." (PMID 40243693, 2025). "Moreover, the exposed workers with the APEX1 Glu/Glu genotype had high tumor biomarkers levels than Asp/Asp and Asp/Glu genotypes." (PMID 36287252, 2023). "Additionally, APEX1 played an essential role in facilitating proliferation, migration, invasion, and tumor growth, and inhibiting apoptosis by modulating Jagged1 in CD133+ GBC-SD cells." (PMID 37283798, 2023). "APEX1 knockdown in CD133+ GBC-SD cells accelerated tumor growth in the xenograft models." (PMID 37283798, 2023). "We found that silencing of APEX1 markedly reduced the body weight and tumor volume of nude mice, which indicated that sh-APEX1 could reduce the tumorigenic characteristics of HCC cells." (PMID 36205565, 2022). "Although previous studies have suggested involvement of APEX1 in tumor progression, it remains unclear whether APEX1 regulates AS in NSCLC." (PMID 35780128, 2022). "Interestingly, a previous in-vitro study has proven that an inhibitor of APEX1, E3330, lead to tumor growth inhibition." (PMID 35311089, 2022). "Moreover, the redox activity of Apex1 mediates tumor growth and migratory properties of pancreatic cancer cells via induction of HIF1α and NF-κB signaling." (PMID 34638302, 2021). "Immunofluorescence results of the tumor samples showed that CPM could inhibit the APEX1/HIF-1α colocalization and interaction in vivo." (PMID 33990544, 2021). "APEX1 expression correlates with the DNA damage repair signaling pathway in HCC tumor tissues." (PMID 32167932, 2020). "We observed incremental increase in the APEX1 mRNA levels with higher tumor grades and stages." (PMID 32167932, 2020). "We suggest that subcellular or extracellular APEX1 expression in ccRCC, HCC, or CC could be used as a potential diagnostic or prognostic marker for tumor progression screening tests." (PMID 31375000, 2019). "In our study, the highest s-APEX1 level was observed in the non-tumor HBV DNA (+) group." (PMID 31375000, 2019). "Several key repair genes play important roles in BER pathway, such as the X-ray repair cross-complementing 1 (XRCC1), 8-oxoguanine DNA glycosylase (OGG1), and apurinic/apyrimidinic endonuclease 1 (APEX1) genes, which are associated with human tumor susceptibility and radiation toxicity." (PMID 29108254, 2017). "However, the DNA repair function of APEX1 was masked by tumor cells." (PMID 35311089, 2022). "This may be the reason for the high expression of APEX1 in tumor cells." (PMID 35311089, 2022).
tumor (continued). "It is unknown whether APEX1 functions in tumor progression by regulation of AS." (PMID 35780128, 2022). "Therefore, we realize that overexpression of APEX1 in tumor cells may be a protective mechanism to resist the accumulation of lipid peroxidation and make tumor cells survival." (PMID 35311089, 2022). "We collected tumor tissues and paracancerous tissues from 20 patients with pathologically confirmed LUAD and detected APEX1 expression by immunohistochemistry." (PMID 40495893, 2025). "In the present study, significant relationships were detected between APEX1 genotypes and the levels of BPDE-albumin adduct and the tumor biomarkers." (PMID 36287252, 2023). "Previous studies found that miR-1293 inhibited the growth of tumor cells by simultaneously targeting BRD4, APEX1, RPA1, and POLD4 via inhibiting the DNA repair pathway." (PMID 36147635, 2022). "Using bioinformatics, we screened six genes for their potential to influence tumor lipid metabolism (ADH1C, APEX1, ME1, S100A10, ACACA, and CYP2C9), and a prognosis model for HCC patients was constructed." (PMID 36456877, 2022). "Western blotting results confirmed that the expression of APEX1 and HIF-1α was inhibited in tumor tissue." (PMID 33990544, 2021). "Apurinic/apyrimidinic endonuclease-1 (APEX1) is a multi-functional protein that regulates several transcription factors, including HIF-1α, that contribute to tumor growth, oxidative stress responses, and DNA damage." (PMID 33990544, 2021). "This demonstrates that APEX1 promotes IL-6 and IL-8 expression in JHH6 cells, suggesting that it influences the tumor microenvironment." (PMID 31375000, 2019). "APEX1 promotes transcriptional activation of HIF-1 and its reduced levels are related to a decrease in tumour volume and FDG uptake, suggesting that it affects glucose metabolism and cellular proliferation." (PMID 23631762, 2013). "Both APEX1 and NOP2 are recognized regulators of tumor metastasis, suggesting a potential mechanism wherein the lymphatic metastasis associated with high MGST1 could be attributed to the overexpression of either APEX1 or NOP2." (PMID 40778224, 2025). "As we expected, Jagged1 overexpression could recover tumorigenic phenotypes in APEX1 knockdown CD133+ GBC-SD cells, including proliferation, migration, invasion, apoptosis, and tumor growth." (PMID 37283798, 2023). "At present, no HIF-1-specific inhibitors currently exist, so targeting APEX1 regulate HIF activity is a promising method to modulate ferroptosis signaling in tumor." (PMID 35311089, 2022). "The results of our study support that targeting of APEX1/HIF-1α and disturbing its interaction may lead to the inhibition of LC tumor pH, migration, and angiogenesis." (PMID 33990544, 2021). "Bioinformatic analyses predicted that APEX1 might interact with cell division cycle 42 (CDC42) and son of sevenless homolog 1 (SOS1), which are involved in tumor metastasis." (PMID 33946672, 2021). "Our study shows that APEX1 is overexpressed in early and advanced stage HCC tumor tissues." (PMID 32167932, 2020). "Furthermore, both APEX1 knockdown and Jagged1 knockdown inhibited CD133+ GBC-SD cells proliferation, migration, invasion, and tumor growth, and promoted CD133+ GBC-SD cells apoptosis, demonstrating that APEX1 and Jagged1 possessed similar biological function in CD133+ GBC-SD cells." (PMID 37283798, 2023). "Thus, if APEX1 expression level is further confirmed as a prognostic marker for HGOS, it might be considered as a new potential therapeutic target for this tumor." (PMID 34207685, 2021). "Differences in patient survival outcome between the APEX1 mRNA and protein expression may be due to differences in APEX1 protein expression in ccRCC cells and total mRNA expression of ccRCC cells and various nontumor cells in tumor tissue sections." (PMID 31375000, 2019).
adenocarcinoma (9 papers, 2012 to 2021). A common cancer characterized by the presence of malignant glandular cells. "Elevation in NANS was positively correlated with adenocarcinoma-associated elevations in APEX1 (apurinicapyrimidinic endonuclease), an important component of base excision repair (BER) pathway and transcriptional modulator of genes that protect against oxidative stress." (PMID 27799870, 2016). "Reductions in SPTA1 and SPTB were indirectly associated with APEX1, which showed a 2.7-fold increase in adenocarcinoma compared to non-malignant tissue and was consistently elevated in 82% of subjects." (PMID 27799870, 2016). "Consistent with our proteomic data, mRNA expression of APEX1, HYOU1, PDIA4, NANS, LRPPRC, EPRS and COPG1 were significantly (Mann–Whitney U < 0.05) higher in adenocarcinoma compared to control whereas mRNA abundance of HBG1, HBG2, HBD, and PTRF were significantly (Mann–Whitney U < 0.05) lower." (PMID 27799870, 2016).
cardiovascular disease (8 papers, 2019 to 2025). "Here, we will review and discuss the important data pertaining to the involvement of APEX1 in cell biology and pathophysiology in the context of cardiovascular diseases." (PMID 40243693, 2025). "Such investigations will help to integrate APEX1 more firmly into our therapeutic armamentarium for combatting cardiovascular diseases." (PMID 40243693, 2025). "Dissecting how APEX1 mediates cytoprotection and antiinflammatory effects across different cardiovascular disease models will clarify whether enhancing its expression or activity could serve as an effective intervention." (PMID 40243693, 2025). "APEX1 and specific cardiovascular diseases will be discussed in the following sections." (PMID 40243693, 2025). "Furthermore, we underscore the potential of APEX1 as a therapeutic target for the treatment of cardiovascular diseases." (PMID 40243693, 2025). "This review aims to present comprehensive coverage of the up-to-date literature concerning the molecular and cellular functions of APEX1, with a particular focus on how APEX1 contributes to the (dys)functions of different cell types during the pathogenesis of cardiovascular diseases." (PMID 40243693, 2025).
neurological disorders (3 papers, 2017 to 2022). "Alternatively, we can use APEX1 inducer or overexpression of APEX1 to resist several neurological diseases by inhibiting the ferroptosis pathway." (PMID 35311089, 2022).
APEX1 also shares sentences with these, for which no sentence is quoted: pancreatic cancer (35 papers); infection (21); head and neck cancer (9); amyotrophic lateral sclerosis (7); myocarditis (6); Cerebral ischemia (5); germ cell tumor (5); inflammation (5); medulloblastoma (5); acute lymphoblastic leukemia (4); acute myeloid leukemia (4); brain tumor (4); clear cell renal cell carcinoma (4); coronary artery disease (4); depression (4); neurodegenerative disease (4); neuropathy (4); diabetic retinopathy (3); ependymoma (3); esophageal squamous cell carcinoma (3); promyelocytic leukemia (3); rhabdomyosarcoma (3); sarcoma (3); B-cell lymphomas (2); bacterial infection (2); Bladder Tumor (2); brain injuries (2); cervical tumor (2); Chronic colitis (2); chronic kidney disease (2).
A further 116 diseases each share a sentence with APEX1 in 2 papers or fewer.